TLR2 (toll like receptor 2)
Diseases named in the same sentence as TLR2 in open-access papers (continued):
Sharing a sentence is not in itself a finding about the gene and the disease.
periodontitis (continued). "In addition, TLR2, a pattern recognition receptor for LTA from S. aureus or LPS from P. gingivalis, is prominently expressed in the pocket epithelium of periodontal tissues with chronic periodontitis and participated in the signaling cascade to upregulate the production of IL-8." (PMID 27413739, 2016). "TLR2 and TLR4 are involved in the immune response against bacterial pathogens (both Gram-positive and Gram-negative bacteria) in cariogenesis and in periodontitis." (PMID 39000094, 2024). "We purified IgG from 16 subjects with elevated or normal levels of aCL and examined their ability to activate TLR2- or TLR4-transfected human embryonic kidney (HEK) cells, and observed that IgG from periodontitis patients with elevated aCL activated HEK-TLR4 cells, but not HEK-TLR2 cells." (PMID 30192824, 2018). "Finally, genotypes are described that protect the mice from periodontitis: the SCID mouse, and mice lacking Tlr2/Tlr4, the Ccr1/Ccr5, the Tnf-α receptor p55, and Cathepsin K by attenuating the inflammatory reaction and the osteoclastogenic response." (PMID 29163477, 2017).
tuberculosis (97 papers, 2006 to 2026). A chronic, recurrent infection caused by the bacterium Mycobacterium tuberculosis. "Studies have also revealed that the TLR2 Arg753Gln polymorphism is associated with increased susceptibility to tuberculosis and other infections." (PMID 41295183, 2025). "Research suggests that abnormal methylation in the promoter regions of TLR2 or genes related to vitamin D metabolism in peripheral blood is associated with tuberculosis risk." (PMID 38680421, 2024). "Individuals carrying rs5743708 (TLR2) had a higher risk of tuberculosis development compared to the control group." (PMID 39339847, 2024). "In previous studies, nucleotide variations in the bovine and buffalo TLR2 gene were associated with somatic cell counts, mastitis, and tuberculosis." (PMID 37370522, 2023). "Hu L., Tao H., Tao X., Tang X., Xu C. TLR2 Arg753Gln gene polymorphism associated with tuberculosis susceptibility: an updatedmeta-analysis." (PMID 35083399, 2021). "In the clinical setting, some polymorphisms in the Tlr2 gene, which attenuates TLR2 signaling, increase the risk of severe tuberculosis caused by Mycobacterium tuberculosis." (PMID 33763386, 2021). "To date, several single nucleotide polymorphisms (SNPs) in TLR2 encoding gene associated with susceptibility to tuberculosis have been verified." (PMID 30733958, 2019). "When stratified by ethnicity, a significant increased tuberculosis risk associated with TLR2 Arg753Gln polymorphism was found in allele genetic model among Caucasian or Asian populations." (PMID 30733958, 2019). "TLR2 Arg753Gln gene polymorphism is one of the most characterized variants that are associated with susceptibility to tuberculosis." (PMID 30733958, 2019). "Vitamin D has been shown to be an important regulatory factor during tuberculosis and has been linked previously to TLR2 function in studies in cell cultures." (PMID 31747871, 2019). "The heterozygotic status and A allele in TLR2 2258 G>A polymorphism were significantly more frequently identified among Turkish children with tuberculosis (TB) than in control cases." (PMID 28118851, 2017). "Our study was the first one to show that the variation of rs3804099 and rs3804100 in TLR2 influences the risk of tuberculosis." (PMID 29348888, 2017). "In the past, the TLR2 R753Q (arginine 753 glutamine) polymorphism has been described in association with susceptibility to several infectious diseases such as tuberculosis, lepromatous leprosy, Lyme disease, Salmonella infection and Candida sepsis." (PMID 26114934, 2015). "Further, the TLR2 Arg753Gln polymorphism was associated with an increased risk of developing tuberculosis." (PMID 26616674, 2015). "One nsSNP in TLR2 (Arg753Gln) has been shown to increase human predisposition to staphylococcal infection, tuberculosis, rheumatic fever and urinary tract infection." (PMID 25496717, 2014). "Risk of developing tuberculosis has been shown to be associated with polymorphisms within the TLR2 gene, particularly within the TIR domain." (PMID 23785280, 2013). "TLR-2 polymorphisms have also been linked to various severe infections, including tuberculosis, leprosy, and septic shock." (PMID 23484049, 2013). "In humans, TLR2 polymorphisms that decrease TLR2 expression were found to predispose people to tuberculosis." (PMID 23401703, 2013). "Subsequent studies identified a significant distinction between tuberculosis patients and healthy controls in TLR2 Arg753Gln polymorphism genotype, indicating that the TLR2 polymorphism influences the susceptibility of Mtb infection." (PMID 21274449, 2011). "One hundred patients with tuberculosis and 100 controls were investigated for the presence of two TLR2 polymorphisms, viz." (PMID 19686607, 2009). "The other SNP, Arg753Gln, was shown to significantly correlate with tuberculosis in a Turkish population; thereby signifying that polymorphism in the TLR2 gene demonstrated an ethnic variation." (PMID 19686607, 2009).
tuberculosis (continued). "This suggests a polymorphism, or polymorphisms in linkage disequilibrium (LD) with TLR2 597C are important in multiple-facets of tuberculosis susceptibility." (PMID 18369480, 2008). "As previously reported, the TLR2 T597C polymorphism was associated with all cases of tuberculosis (control vs. all isolates; OR = 1.28 [95% C.I. 1.01–1.62], P = 0.045)." (PMID 18369480, 2008). "TLR2 T597C genotype comparison between control and tuberculosis groups when the major allele (T) is dominant." (PMID 18369480, 2008). "We also found that individuals with the C allele of TLR-2 T597C allele were more likely to have tuberculosis caused by the East-Asian/Beijing genotype (OR = 1.57 [95% C.I. 1.15–2.15]) than other individuals." (PMID 18369480, 2008). "Tlr9 and Tlr2 double knockout mice display a more pronounced susceptibility to infection by tuberculosis than single gene knockout mice." (PMID 16608528, 2006). "TLR2 (−196 to −174) del polymorphism may contribute to drug resistance in tuberculosis given that it is associated with disease severity and is found in a higher proportion of drug-resistant cases of the disease." (PMID 38481606, 2023). "This may be the first study to analyze the immune response to drug-resistant tuberculosis patients by analyzing TLR2 (−196 to −174) del and TLR1 743 A > G gene polymorphism." (PMID 38481606, 2023). "There were various TLR2 polymorphisms found in tuberculosis patients." (PMID 38099246, 2023). "TLR2 (−196 to −174) del polymorphism may have a role in contributing to drug resistance in tuberculosis, though the exact mechanism is still unknown, given its correlation with disease severity and the higher frequency in drug-resistant tuberculosis cases." (PMID 38481606, 2023). "Our results show, the mutation of TLR2 gene may play an important protective role in the incidence of tuberculosis, which should be further explored." (PMID 29348888, 2017). "We also detected an association of TLR2 gene with tuberculosis (rs5743708; 3.19 [2.03–5.02])." (PMID 26524966, 2015). "Population-based case–control studies have shown that the polymorphisms of TLR2 could influence poor outcomes in a number of diseases, such as cancer, tuberculosis, and infective endocarditis." (PMID 26616674, 2015). "Interestingly, the converse result was obtained when a Turkish cohort of tuberculosis patients was genotyped for the TLR2 polymorphism." (PMID 22529866, 2012). "Toll-like receptor 2 (TLR2) is capable of recognizing pathogen-associated molecular patterns expressed by Mycobacterium tuberculosis (Mtb), such as a 19-kDa lipoprotein, lipoarabinomannan, and soluble tuberculosis factor." (PMID 20113509, 2010). "In addition, significant downregulation of Toll-like receptor 2 (TLR2) after silica exposure may contribute to increased susceptibility to tuberculosis." (PMID 37901242, 2023). "To date, a series of studies were conducted to investigate the association between TLR2 (Toll-like receptor 2) Arg753Gln gene polymorphism and tuberculosis (TB)." (PMID 30733958, 2019). "Association of TLR2 polymorphism with TB has been reported in human, and in the case of Cattle, SNPs in TLR2 and TLR4 genes have been associated with susceptibility to paratuberculosis infection." (PMID 27284220, 2016). "Furthermore, associations between TLR2 gene polymorphisms and tuberculosis have been reported for a range of different human populations, suggesting that changes in TLR2 expression may be involved in susceptibility to disease." (PMID 26913035, 2016). "In view of the role of TLR2 activation in host defense against mycobacteria, the present study was conducted to examine whether TLR2 polymorphisms could account for the increased prevalence of tuberculosis in Indian patients." (PMID 19686607, 2009). "Previously, we analyzed the association of SNPs in TLR2 and TLR4 genes in samples of HIV patients and HIV–tuberculosis patients in Eastern Europe and Central Asia." (PMID 37606452, 2023).
tuberculosis (continued). "The objective of this study is to analyze the association between TLR2 deletion (−196 to −174) and TLR1 743 A > G gene polymorphism with drug resistant tuberculosis (PTB, MDR-TB, and XDR-TB) in a population from Agra, Uttar Pradesh." (PMID 38481606, 2023). "Our data indicate that Pam2CSK4 targeting TLR2, which has been shown to be effective in tuberculosis vaccines, is the optimal adjuvant for the SARS-CoV-2 nanoparticle vaccine, paving the way for an immediate clinical trial." (PMID 36569949, 2022). "Recombinant BCG was found to induce robust MHC class II-dependent antigen presentation on CD4 T cells in vitro, activating TLR2 and thus leading to a better protection against tuberculosis in mice." (PMID 36295826, 2022). "Cytokine production stimulated by LPS can also be reduced by cross-tolerance signaling when TLR2 is exposed to alternate ligands such as lipopeptides, lipoarabinomannans, soluble tuberculosis factor, lipoteichoic acids, and zymosan." (PMID 35100875, 2022). "Polymorphisms in the TLR2 and TLR4 genes are mostly associated with a susceptibility to tuberculosis." (PMID 36611413, 2022). "In tuberculosis, the innate immune response toward Mycobacterium tuberculosis(Mtb) largely relies on robust macrophage activation via TLR‐2, NF‐κB, and downstream inflammasome signaling." (PMID 34133077, 2021). "A strongly increased TLR2 gene expression was found in lymph node of patients suffering from tuberculosis compared to healthy subjects." (PMID 33057074, 2020). "To get closer to the nature of tuberculosis with involvement of different cell types including antigen-presenting cells such as DCs, we simulated a TLR2 inhibition using a blocking anti-TLR2-antibody." (PMID 33057074, 2020). "The parent BCG85B was then compared with BCG85C5 vaccine using wt- and TLR-2 KO mice to determine if TLR-2 was required for the efficacy of BCG85C5 against tuberculosis challenge of mice." (PMID 31396406, 2019). "To investigate the role of TLR2 during mycobacterial infection, we analyzed the response of tlr2 zebrafish mutant larvae to infection with Mycobacterium marinum (Mm), a close relative to Mtb, as a model for tuberculosis." (PMID 31747871, 2019). "In accordance, a previous study in human peripheral blood mononuclear cells and an in vivo mouse model for tuberculosis showed a switch in host cellular metabolism toward aerobic glycolysis after mycobacterial infection that is dependent on TLR2." (PMID 31747871, 2019). "We found that TLR2 Arg753Gln gene polymorphism increases susceptibility to TB in overall, which support the fact that TLR2 plays an important role in host immune response against tuberculosis." (PMID 30733958, 2019). "Further studies are needed to address the question of ESAT-6 and TLR2 relationships in tuberculosis and better characterize the cellular targets through which ESAT-6 inhibited M1A MΦ pro-inflammatory phenotype." (PMID 30283745, 2018). "TLR2 and TLR1 act together to mediate responses to M. tuberculosis and the role of TLR1/2 gene variants in the predisposition to tuberculosis has been investigated." (PMID 25312698, 2015). "In total, we found two results that withstood multiple testing correction: IL4 in pooled model and TLR2 for tuberculosis." (PMID 26524966, 2015). "Among them, the most important receptor is TLR2 which is involved in the production of IL-10 during tuberculosis." (PMID 24695099, 2014). "High TLR2 and TLR4 expression during anti-tuberculosis treatment associated with a moderate form of disease suggests that these receptors were seems likely beneficial to the patients because such TLRs can induce the production of pro-inflammatory cytokines." (PMID 24558401, 2014). "Although synergistic effects for TLR2 and TLR4 have been described for tuberculosis, malaria, and lupus, our study is the first to associate a genetic trait for TLR2 and TLR4 SNPs with susceptibility to meningitis." (PMID 23691182, 2013).
tuberculosis (continued). "In conclusion, in the present work we have shown that mRNA levels of Coronin-1, Sp110 and TLR-2 are increased in patients with tuberculosis and in close contacts of patients with latent tuberculosis infection." (PMID 20718957, 2010). "The mRNA expression of Coronin-1, Sp110 and TLR-2 was significantly higher in patients with active tuberculosis and subjects with latent disease compared to the uninfected ones." (PMID 20718957, 2010). "In this study, we observed an increased expression of TLR-2, Coronin-1, and Sp110 mRNA levels in PBMCs of patients with tuberculosis and in close contacts of patients that had latent tuberculosis infection." (PMID 20718957, 2010). "Our data suggest that Coronin-1, Sp110 and at least Toll-like receptor-2 molecules are involved in the infectious process of tuberculosis." (PMID 20718957, 2010). "TLR2 -975C/T was protective against tuberculosis, due to the attenuation of TLR2 signaling." (PMID 37606452, 2023). "Given that the TLR2 gene encompasses a broad spectrum of pathogen-associated molecular pattern (PAMP) recognition receptors, including triacylated oligopeptides and diacylated lipopeptides, it has been widely studied in tuberculosis." (PMID 37888601, 2023). "However, other studies have shown that TLR2 agonist-adjuvanted tuberculosis vaccine can induce a Th1-biased immune response." (PMID 36569949, 2022). "However, in several infectious diseases, such as tuberculosis, malaria, and toxoplasmosis, TLR2 and TLR4 have been considered important in the development of the inflammatory response and pathology." (PMID 31119102, 2019). "Moreover, ATT treatment has been shown to increase the expression of TLR2 and TLR4 in tuberculosis, indicating their association with disease protection." (PMID 30218032, 2018). "Also, PE-PGRSs have been shown to promote entry of M. tuberculosis into macrophages via TLR2, an important step in the pathogenesis of tuberculosis." (PMID 28348055, 2017). "However, our results highlight that TLR2 participates in the biological events leading to the activation of immune defense against tuberculosis." (PMID 24130733, 2013). "These diverse data indicate that further studies are needed to elucidate whether TLR-2 is beneficial or harmful in humans in regard to tuberculosis." (PMID 20718957, 2010). "The TLR2 polymorphism R753Q, associated with tuberculosis, was not shown to be different between the control or lung disease group." (PMID 16608528, 2006). "Pulmonary tuberculosis (TB) remains a global health threat, with individual genetic determinants like Toll-like receptor 2 (TLR2) gene variations potentially modulating immune responses to Mycobacterium tuberculosis." (PMID 42075681, 2026). "Tuberculosis (TB), an essentially lung disease, was the disease most studied for the SNP rs3804100 in the TLR2 gene in different populations." (PMID 37895256, 2023). "Interaction with Toll like receptor 2 (TLR2) promotes secretion of inflammatory chemokines and cytokines, which are key in the immunopathogenesis of tuberculosis (TB)." (PMID 33467487, 2021). "rs7696323 is located in the intron of the TLR2 gene located near 4q31.3 (precise position: 154605745) and rs11536889 is located in the 5’UTR of the TLR4 gene located near 9q33.1 (precise position: 120478131)has nothing to do with susceptibility of tuberculosis in Chinese Han children." (PMID 29348888, 2017). "Analysis of a polymorphic guanine-thymine (GT) repeat located upstream of the TLR2 translational start site correlated shorter GT repeats with development of tuberculosis (TB) and lower TLR2 expression." (PMID 23785280, 2013). "The adaptor protein TIRAP mediates down stream signalling of TLR2 and 4, and polymorphisms in the TIRAP gene (TIRAP) have been associated with susceptibility and resistance to tuberculosis (TB) in adults." (PMID 19693265, 2009).